BDNF (brain derived neurotrophic factor)
Diseases named in the same sentence as BDNF in open-access papers (continued):
Sharing a sentence is not in itself a finding about the gene and the disease.
Cognitive impairment (continued). "In a murine model of VaD, low-frequency (inhibitory) rTMS was able to improve cognitive deficit through the up-regulation of the hippocampal brain-derived neurotrophic factor (BDNF) and the expression of the N-methyl-d-aspartate glutamate receptor." (PMID 32340195, 2020). "Traumatic brain injury (TBI): curcumin reduced oxidative damage, normalized levels of BDNF, synapsin I, and CREB and counteracted the cognitive impairment caused by TBI." (PMID 32927725, 2020). "In the present study, we found that prenatal stress increased the blood corticosterone level, decreased the hippocampal GR and BDNF expression and induced hippocampus-dependent cognitive impairments in mouse offspring." (PMID 32781547, 2020). "In this present study, we found that PGC-1α improved synaptic plasticity, the energy metabolism of hippocampal neurons, and promoted the expressions of BDNF and mitochondrial antioxidants, which all contributes to alleviate the cognitive impairment." (PMID 32194838, 2020). "The positive effects of exercise on the BDNF level and cognitive functions have also been demonstrated in elderly patients with cognitive deficits, such as mild cognitive impairment." (PMID 32565776, 2020). "Otherwise, the regulation of the BDNF/ERK1/2 pathway has also been observed in cognitive impairment induced by other cerebral diseases, such as TBI, which causes neurodegeneration due to mechanical impact from external forces." (PMID 32754029, 2020). "Both of these increased the expression levels of BDNF and cured the cognitive impairment measured by behavioural analysis in the BCCAO‐induced VaD rat model." (PMID 32374084, 2020). "Results of our study suggest that HupA can increase the hippocampal NGF, BDNF and NT-3 levels, which is related to its protective effect on cognitive impairment of rats after isoflurane anesthesia." (PMID 32049185, 2020). "FGF2-Akt and BDNF-TrkB signaling pathways were reactivated by Rg1 in the hippocampus and prefrontal cortex to inhibit neuronal apoptosis and prevent cognitive deficits." (PMID 32410834, 2020). "In the present study, we demonstrate that AOM enhances adult hippocampal neurogenesis and improves cognitive impairment via inducing BDNF/TrkB/AKT signaling pathway in post–ischemic stroke treatment." (PMID 33537297, 2020). "Increasing respective concentrations of CREB and BDNF in the hippocampal region alleviates cognitive impairments and memory problems." (PMID 32731545, 2020). "Collectively, our study supports the notion that NMDAR/Ca2+/calpain is mechanistically involved in anesthesia and surgery-induced BDNF/TrkB signaling disruption and cognitive impairments in aging mice, which provides one possible therapeutic target for POCD." (PMID 31948437, 2020). "MiR-134-mediated post-transcriptional regulation of CREB1 and BDNF prevents cognitive deficits in chronic unpredicted mild stress model (CUMS)." (PMID 33096634, 2020). "Maternal chewing during prenatal stress attenuated elevated circulating corticosterone level, increased the hippocampal GR and BDNF expression and ameliorated cognitive impairments in the offspring induced by prenatal stress." (PMID 32781547, 2020). "Nevertheless, the relationship between BDNF and cognitive function is well established and low serum BDNF levels have been attributed to cognitive impairment in the elderly." (PMID 32707771, 2020). "Impairments in the BDNF/TrkB signaling are highly correlated with cognitive impairment and dendritic spine changes during aging." (PMID 32537724, 2020).
Cognitive impairment (continued). "The functional significance of the Fingolimod-induced BDNF release is marked by its ability to improve the cognitive impairment typical of different neurological diseases, e.g., Alzheimer’s and Huntington’s diseases." (PMID 32349283, 2020). "Fucosterol co-infusion ameliorated sAβ1-42-induced cognitive deficits in aging rats by modulating BDNF signaling." (PMID 32630301, 2020). "By contrast, MMSE and MoCA scores in PD patients were positively correlated with NGF and BDNF levels and negatively correlated with NSE levels, confirming these close associations with PD severity and cognitive impairment." (PMID 33329296, 2020). "The elevation of BDNF is beneficial for improvements in neuroplasticity and lower ratios of cognitive deficits." (PMID 32265642, 2020). "Studies demonstrating that BDNF p.Val66Met SNP is found to be associated with both NPS and cognitive impairments in AD are consistent with a biological understanding of NPS, and previous evidence linking BDNF and NPS." (PMID 33584494, 2020). "The effect of apigenin in alleviating poststroke cognitive impairment was found to involve the epigenetic induction of brain-derived neurotrophic factor (BDNF) through HDAC inhibition." (PMID 33383852, 2020). "Manganese (Mn) overexposure produces long-term cognitive deficits and reduces brain-derived neurotrophic factor (BDNF) in the hippocampus." (PMID 33033239, 2020). "Bailey3 reported that Mn overexposure during development produces long-term cognitive deficits and reduces brain-derived neurotrophic factor (BDNF) in the hippocampus." (PMID 33033239, 2020). "EE improved the sevoflurane-induced cognitive impairments by enhancing hippocampal histone acetylation and BDNF expression." (PMID 32813852, 2020). "Our study was designed to examine the relationship between Brain‐Derived Neurotrophic Factor (BDNF) genotypes (rs6265, Val66Met), BDNF plasma levels, and cognitive impairment in Chinese patients with panic disorder (PD)." (PMID 33047489, 2020). "Other flavonoids like naringenin and tea polyphenols are reported to possess protective effects against oxidative stress-triggered cognitive impairment through up-regulating the protein kinase B(AKT)/CREB/BDNF signaling pathway." (PMID 32405353, 2020). "Fucoxanthin ameliorated scopolamine-induced and Aβ oligomer-induced cognitive impairments in mice, possibly by inhibiting AChE activity and OS, modulating ChAT activity, and increasing BDNF expression." (PMID 32630301, 2020). "In the mouse model, BDNF has been shown to be required for neurogenesis in the hippocampus and a declined BDNF level was noted in the ageing adults, indicating a possible connection of low BDNF to reduced memory, neurodegeneration and cognitive impairments." (PMID 32806562, 2020). "Sevoflurane was also reported to decrease the expression of BDNF and induced cognitive impairment in 18 month-old rats." (PMID 32793611, 2020). "Together, the data suggest that decreased BDNF signaling possibly mediates psychostimulant-induced cognitive deficits." (PMID 31396113, 2019). "The effects of MK-801 on neuron-derived BDNF expression and of risperidone on MK-801-induced cognitive impairment and changes in BDNF expression are unclear." (PMID 31396062, 2019). "Exposure of rats to LPS during gestation induced cognitive deficits in the young offspring, elevated BDNF levels and decreased neurotensin levels." (PMID 31036753, 2019). "Similar to depletion of C/EBPβ, inhibition of δ-secretase activity by the C189S mutant also restored dendritic spines and synapse density, resulting in alleviation of LTP impairments and cognitive deficits induced by BDNF depletion in the hippocampus." (PMID 31315045, 2019). "In our model, some factors promoted the downregulation of BDNF, leading to long-term cognitive impairment after anaesthesia and surgery." (PMID 31708739, 2019). "Animal models and clinical trials have also shown that BDNF levels are positively correlated with cognitive impairment." (PMID 31420036, 2019).
Cognitive impairment (continued). "People with cognitive impairment have a lower level of BDNF than those with normal cognitive function." (PMID 31137805, 2019). "MDD patients show cognitive deficits, and altered BDNF regulation has a relevant role in neurocognitive functions." (PMID 31636250, 2019). "Mechanisms through which acupuncture improves cognitive impairment in AD include attenuation of Aβ deposits, upregulation of BDNF expression, and regulation of cell proliferation and neural plasticity in the brain." (PMID 31379957, 2019). "They found that madecassoside, one of the two major active constituents of ECa 233, enhanced learning and memory behavior and up-regulation of PSD-95, p-NMDAR1 (NR1 subunit), p-CaMKII, p-PKACβ, p-CREB and BDNF in the cognitive-impairment model." (PMID 31182820, 2019). "BDNF mRNA and protein levels are also reduced in cognition-related structures such as hippocampus and frontal cortex, which corroborates BDNF depletion to be involved in the cognitive deficit leading to AD dementia." (PMID 30117106, 2019). "As induces hippocampal neuronal apoptosis through an up regulated none morphogenic protein 2 (BMP2), Smad dependent attenuation of BDNF TrkB pathway resulting cognitive impairments." (PMID 31199848, 2019). "Previous studies have shown that stress reduces neurogenesis and the level of the hippocampus of BDNF, leading to cognitive impairment and increased stress in individuals." (PMID 34466479, 2019). "We also examined the effects of risperidone on MK-801-induced cognitive impairment and changes in BDNF expression." (PMID 31396062, 2019). "Recent studies have shown that BDNF levels are significantly decreased in individuals with cognitive decline-related diseases, such as mild cognitive impairment, Alzheimer disease, and Huntington’s disease." (PMID 30659208, 2019). "Intriguingly, delayed clenbuterol treatment also improved cognitive impairments by normalization of hippocampal CREB/BDNF, PSD95, and GluN2B." (PMID 31354429, 2019). "In the present study, we investigated effects of GQ1b-induced BDNF up-regulation on cognitive impairment, Aβ pathology, and tau pathology in AD." (PMID 31186474, 2019). "Telmisartan, a unique ARB with PPARγ-stimulating activity, has been shown to counteract cognitive impairment through the up-regulation of BDNF/TrkB in the hippocampus, partially due to its ability to activate PPARγ." (PMID 31614739, 2019). "This is a critical step in facilitating the establishment of the clinical threshold values of serum BDNF in cognitive disorders, and eventually propelling the use of serum BDNF in the clinics, enabling the translation of biomarker research." (PMID 30634650, 2019). "The present study evaluated the possibility of developing a new natural medicine by investigating cognitive impairment, cell function and survival, and BDNF regulation during the neuroprotective effects of GEGR in an SP-induced AD model." (PMID 31623364, 2019). "Conversely, administration of BDNF attenuates memory deficits induced by injecting Aβ peptide and a neurotrophin mimetic improves cognitive impairment in AD mice (Prior, Dargusch, Ehren, Chiruta, & Schubert, 2013)." (PMID 30746828, 2019). "Clinical studies show that BDNF expression is decreased in patients presenting with cognitive impairment after anaesthesia and surgery." (PMID 31708739, 2019). "Given that BDNF protects Aβ-induced neuronal cell death and ameliorates cognitive deficits in rodents and primate models of AD30,46." (PMID 31186474, 2019). "A study reported that laser acupuncture on GV20 and HT7 for 14 days excited the cholinergic system and increased CREB, BDNF, and B-cell lymphoma 2 (Bcl-2) levels, thereby improving cognitive impairment in rats." (PMID 31379957, 2019). "In conclusion, hypertension is a well-known factor that induces brain abnormalities and cognitive impairment in old and middle-aged persons and alters structural and functional changes in the hippocampus by reducing BDNF-TrkB signaling." (PMID 31234585, 2019).
Cognitive impairment (continued). "Substantial evidence implicates that chronic restraint stress reduces hippocampal neurogenesis and mRNA levels of BDNF and induces hippocampus-dependent cognitive deficits." (PMID 34466479, 2019). "On the other hand, dietary restriction (i.e., the maintenance of a balanced diet) or addition of supplementary substances (e.g., omega-3 fatty acids; resveratrol) can induce an increase in BDNF levels and reduce cognitive impairment in animal models." (PMID 30117106, 2019). "An insufficient supply of endogenous BDNF leads to neurodegeneration, cognitive impairment, and sharp decreases in neuronal proliferation in SGZ." (PMID 31881998, 2019). "Vildagliptin reversed diabetes-induced decrease of p-Akt, p-GSK-3β, brain-derived neurotrophic factor and nerve growth factor, thus against cognitive deficits and memory impairment." (PMID 31237881, 2019). "A clinical study reported that BDNF protein expression decreased after anaesthesia and surgery in patients with cognitive impairment." (PMID 31708739, 2019). "Reduced LPS-induced microglial activation and/or increased BDNF synthesis by estrogens, especially in the cortical and hippocampal regions, possibly protected our female animals from overpruning-induced cognitive deficits." (PMID 31057438, 2019). "Collectively, our findings reveal a critical role of BDNF signaling in the mother to offspring transmission of HFD-dependent cognitive deficits." (PMID 31641124, 2019). "The prolonged repression of BDNF expression had a significant impact on long-term cognitive impairment induced by anaesthesia and surgery, and this process was highly related to H3K9 trimethylation." (PMID 31708739, 2019). "We have recently shown an increase in CSF BDNF in mild cognitive impairment patients as compared to AD patients suggestive of a complex relationship involving preclinical and clinical stages of the disease." (PMID 30804738, 2019). "In our scopolamine-induced cognitive impairment model, SC and RF also ameliorated with activation of BDNF and its downstream signaling pathway (CREB/ERK/AKT)." (PMID 31547274, 2019). "For example, it has been reported previously that HS injection prevents cognitive deficits in animal models following traumatic brain injury, effects which were proposed to involve antioxidant activity and activation of BDNF-related synaptic plasticity." (PMID 31103039, 2019). "PD patients that were BDNF Met carriers suffered cognitive impairment more frequently and therefore had lower Mini-Mental State Examination scores than Val/Val homozygotes." (PMID 31365694, 2019). "We are currently investigating age-related changes in neurotrophin signalling pathways and treatments in the hope to better understand the functional role of BDNF throughout stroke-induced cognitive impairments." (PMID 31191635, 2019). "Higher serum levels of neurotrophic factors, such as brain-derived neurotrophic factor (BDNF) and insulin-like growth factor-1 (IGF-1), are associated with lower incidence of dementia and lower risk of progression in cognitive impairment in elderly people." (PMID 29751661, 2018). "A decrease in brain derived neurotrophic factor (BDNF) in early MS patients has been demonstrated and was associated with cognitive impairment in one recent study." (PMID 29872382, 2018). "In recent studies, curcumin nanoparticles have also been prepared, which alleviate the condition of cognitive impairment by recovering BDNF levels via Akt/GSK-3β signaling pathways." (PMID 30262792, 2018). "For example, a recent report showed that increasing pro‐BDNF levels leads to cognitive deficits (Buhusi, Etheredge, Granholm & Buhusi, 2017)." (PMID 29749079, 2018).
Cognitive impairment (continued). "Cognitive impairments were improved in aged mice due to an increase in CREB and BDNF levels caused by administration of curcumin." (PMID 30262792, 2018). "Cognitive impairment in schizophrenia is related to various factors, such as the psychotic severity, aging, medication, and brain-derived neurotrophic factor (BDNF)." (PMID 29896133, 2018). "To better understand how reduced BDNF expression contributes to sevoflurane-induced cognitive impairments in offspring, we examined the changes in one key component of BDNF-regulated signaling cascades, Akt." (PMID 29773978, 2018). "Δ9-THC, the principal active component of cannabis, was shown to promote upregulation of BDNF expression whereas increased levels of BDNF were shown to rescue the cognitive deficits promoted by Δ9-THC administration." (PMID 30546297, 2018). "Positive correlations between serum BDNF concentration and severity of the symptoms and cognitive deficits in the patients with PD have been reported." (PMID 30463271, 2018). "Together, these findings suggested that ICS II attenuates CCH-induced cognitive deficits by inhibiting the amyloidogenic pathway via involvement of BDNF/TrkB/CREB signaling and up-regulation of PPARα and PPARγ in rats." (PMID 30405422, 2018). "Using the risk allele framework one would predict that learning and cognitive flexibility would be impaired in BDNF 66Met mice, potentially due to cognitive impairment or inefficiency." (PMID 29909248, 2018). "On the other hand, increased plasma concentration of BDNF has been observed in AD and mild cognitive impairment patients." (PMID 30463271, 2018). "Inhalation anesthesia with sevoflurane increased RAGE expression and decreased a BDNF level in the Aβ-treated hippocampus, suggesting that the changes in these two protein expressions were partly related to cognitive impairment." (PMID 30402039, 2018). "Recently, low serum level of brain-derived neurotrophic factor (BDNF) was found to be associated cognitive impairments, and genetic variations in the BDNF gene were found to protect against cognitive impairments in cancer patients receiving chemotherapy." (PMID 29864112, 2018). "Recent study suggests that brain-derived neurotrophic factor (BDNF) is correlated with cognitive deficits in T2DM patients." (PMID 29423073, 2018). "After accounting for known confounders of self-reported cognitive impairment, the GEE model revealed that BDNF levels were found to be associated with self-perceived concentration deficit." (PMID 29258453, 2017). "This study sought to investigate the changes of plasma BDNF levels and self-perceived cognitive impairment in ESBC patients receiving chemotherapy." (PMID 29258453, 2017). "ELS is known to impact on BDNF expression in the hippocampus, reinforcing the association with ELS-induced cognitive deficits that have been described." (PMID 28261058, 2017). "Numerous studies have reported the possible role of BDNF in the pathogenesis of various cognitive disorders, such as Alzheimer’s disease." (PMID 29258453, 2017). "To assess the role of BDNF/TrkB pathway in amelioration of cognitive deficit induced by acupuncture, we used specific tyrosinase inhibitor K252α to block BDNF/TrkB pathway." (PMID 28243312, 2017). "This demonstrates individuals with some cognitive impairment should count on larger doses of exercise to achieve similar responses on BDNF-related executive processes than those displaying a natural aging decline." (PMID 28469588, 2017). "In the present study, the hippocampal LTP was impaired in Hx rats showing cognitive impairments with decreased BDNF expression in the hippocampus." (PMID 28767193, 2017). "It is worth noting that improving levels of DCV cargos (i.e., BDNF and somatostatin) partially recover AD-altered networks, preventing cognitive deficits and favoring Aβ clearance." (PMID 28701919, 2017).